SMARCA2 (SWI/SNF related BAF chromatin remodeling complex subunit ATPase 2)
Diseases named in the same sentence as SMARCA2 in open-access papers (continued):
Sharing a sentence is not in itself a finding about the gene and the disease.
tumor (continued). "By analysing the expression of five subunits of the SWI/SNF complex (INI1/SMARCB1, SMARCA2, SMARCA4, ARID1A, PBRM1), we further explored the relevance of alterations in chromatin remodelling in glandular differentiated tumours." (PMID 32198650, 2020). "For those genes deregulated after OOS treatment, PTGDR and SMARCA2 turned out to be more expressed in AML than in any other tumor type, conversely, SERPINE1 was less expressed in AML than in most other tumor types." (PMID 31091680, 2019). "Our results demonstrate that expression of SMARCA4 and SMARCA2 have a high prognostic value and challenge the broadly accepted general role of SMARCA4 as a tumor suppressor." (PMID 29391527, 2018). "This list includes known tumour suppressors such as the nuclear receptor NR3C2, the helix-loop-helix transcription factor TCF21, and SMARCA2 (also known as BRM), a member of the SNF/SWI chromatin remodelling complex." (PMID 27562343, 2016). "The SMARCA4/SMARCA2 allosteric inhibitor, FHD-286, effectively suppressed the proliferation of a broad collection of patient-derived AML cells, promoted differentiation, and decreased tumor growth in vivo." (PMID 38390898, 2024). "However, in multiple myeloma cells, PFI-3 displaced SMARCA2 and the oncogenic driver, NSD, from chromatin, suppressing oncogenic gene expression and tumor growth." (PMID 38390898, 2024). "For example, a GSH-inducible SMARCA2/4-targeting PROTAC demonstrates selective degradation of SMARCA2/4 in cancer cells, promoting DNA damage and apoptosis while inhibiting tumor growth in xenograft models without adverse effects on normal cells." (PMID 39649701, 2024). "Given SMARCA2 degradation failed to meet expectations for tumour efficacy, combinations were explored, which led to identification of in vitro sensitisation to apoptosis through combination with MCL1 inhibitors." (PMID 36720862, 2023). "The SMARCA2 gene is a very important catalytic subunit in the SWI/SNF complex, essential for SWI/SNF activities, such as cellular metabolism (including drug metabolism), differentiation, development, DNA repair, tumor angiogenesis, progression or metastasis." (PMID 35289322, 2022). "Tumor growth inhibition was dependent upon SMARCA2 degradation and was not due to non-specific effects of the chemical scaffold, as VHL and SMARCA2/4 -binding defective analogs A857 and A858 were not efficacious." (PMID 36357397, 2022). "Applying the same dose and regimen as used in the SMARCA4mut xenograft studies, A947 did not result in tumor growth inhibition in SMARCA4wt Calu-6 xenografts despite achieving greater than 95% degradation of SMARCA2 protein." (PMID 36357397, 2022). "In detail, male sex, T3 and T4 stage, moderate and poor differentiation, tumor ≥ 2 cm, Ki67 ≥ 15%, SOX-2 negative expression, middle lobe lesion and adenocarcinoma were relative risk factors affecting SMARCA2-negative expression (P < 0.05)." (PMID 35289322, 2022). "High frequency of SMARCA2 mutations also occur in non-melanoma skin cancers and are associated with damage from UVR, suggesting that SMARCA2 has a tumor-suppressive function when skin is exposed to the sun." (PMID 35323214, 2022). "In NSCLC, male sex, T3 and T4 stage, moderate and poor differentiation, tumor ≥ 2 cm, Ki67 ≥ 15%, SOX-2 negative expression, middle lobe lesion and adenocarcinoma were relative risk factors affecting SMARCA2-negative expression." (PMID 35289322, 2022). "Only for five genes, namely KAT2A, SMARCA4, BAZ1A, ATAD2 and TRIM28, we observed consistently higher levels and for two genes—KAT2B and SMARCA2—lower levels, respectively, regardless of the tumor type." (PMID 35049055, 2022). "An AlphaScreen-based assay used to screen a large compound library also identified a SMARCA2 BRD inhibitor known as DCSM06, which may provide new information about the tumor suppressor functions of this protein." (PMID 34298819, 2021).
tumor (continued). "Of the 16 datasets with highly significant changes (P ≤ 0.0001 and |FC| ≥ 2), 13 (81%) presented lower levels of SMARCA2 transcript in tumor samples than in non-tumor samples." (PMID 29391527, 2018). "In stark contrast, SMARCA2 transcript levels were decreased in tumors compared to normal samples in 15 of the 22 tumor types analyzed and was not overexpressed in any type of tumor." (PMID 29391527, 2018). "Despite no changes in tumor growth in the SCLC-A xenografts, western blot and IHC analysis of tumors confirmed on-target drug activity of AU-24118 as indicated by efficient loss of SMARCA4, SMARCA2, and PBRM1." (PMID 38328238, 2024). "Mechanistically, it has been suggested that both concurrent or nonconcurrent deletion of SMARCA4 and SMARCA2 could further accelerate the process of poor tumor differentiation and EMT." (PMID 35289322, 2022). "We first examined genes that may render cell-growth advantage through analysis of our CRISPR/Cas9 perturbation screen in JeKo-1 cells and found that many critical tumor suppressors were located on chr9, including CDKN2A, SMARCA2, FBXO10, and TOR1B (z score ≥ 1)." (PMID 34882582, 2022). "This might explain the lack of a tumor stem cell phenotypic differentiation direction in SMARCA2-negative NSCLC in our study." (PMID 35289322, 2022). "It has been hypothesized that the dual deficiency in key members of the SWI/SNF complex (e.g., SMARCA4 and SMARCA2, or SMARCB1 and SMARCA2) can induce dedifferentiation from a normal cell or a low-grade tumor into an aggressive high-grade tumor with small cell and/or rhabdoid features." (PMID 35200537, 2022). "Cluster 1 was characterized by upregulation of tumor-suppressing genes: HNF1B, CCNDBP1, PATJ, EPB41L3, MARVELD2, PTEN in conjunction with cell-cycle genes – GSPT1, GPR19, EAPP, KIT, CDKL1, and stem cell markers – RBBP5, NANOG, NCSTN, ERG, including quiescent stem cell markers—FOXP1, SMARCA2." (PMID 36348001, 2022). "Likewise, SMARCA2, GLCE, and EFEMP1 showed tumor-suppressor and anti-proliferative activities." (PMID 32610656, 2020). "Thus the tumor-promoting functions of SMARCA4 and SMARCA2 might be unique to ccRCC." (PMID 28445125, 2017). "Immunohistochemistry (IHC) revealed tumor cells negative for AE1/AE3, PAX8, OCT4, CD34, SALL4, chromogranin, synaptophysin, NGFR CD20, WT1, cyclin D1, and SATB2, with lost expression of BRM (SMARCA2) and retained expression of INI1 (SMARCB1) and BRG (SMARCA4)." (PMID 39726498, 2024). "Immunohistochemically, the tumor cells totally lacked SMARCA4 and BRM (SMARCA2); were negative for TTF1, AE1/3, Claudin4, desmin, MyoD1, myogenin, CD99, CD56, and WT‐1 proteins; and were weakly positive for synaptophysin." (PMID 36523385, 2022). "Despite no changesin tumor growth in the SCLC-A xenografts, immunoblotting and IHC analysis oftumors confirmed on-target drug activity of AU-24118 as indicated by efficientloss of SMARCA4, SMARCA2, and PBRM1." (PMID 39029462, 2024).
cancer (146 papers, 2009 to 2026). A tumor composed of atypical neoplastic, often pleomorphic cells that invade other tissues. "Exploiting synthetic lethal interactions caused by specific mutations offers more promise, as in SMARCA4‐mutant cancers reliant on SMARCA2 or SMARCB1‐mutant tumors vulnerable to ncBAF‐targeting." (PMID 40181550, 2026). "For example, SMARCA4-deficient cancer cells lose tumorigenicity and undergo cell cycle arrest and senescence upon the depletion of SMARCA2." (PMID 38390898, 2024). "SMARCA4 and SMARCA2 have emerged as oncogenic dependencies in certain cancer types, with SMARCA4 specifically being implicated in cancer metastasis." (PMID 39174852, 2024). "In SMARCA4-deficient cancers that retain SMARCA2 expression, several reports have shown that SMARCA2 acts as a synthetic lethal target, making it a potential therapeutic vulnerability." (PMID 37093326, 2023). "Cancer cells deficient in either SMARCA4 or SMARCA2 are vulnerable to genetic ablation of the remaining paralog, a synthetic lethality that is being explored as a potential therapeutic strategy." (PMID 37210563, 2023). "Different from the A1186T mutation, cancer cells carrying homozygous G1232D or G1232S mutations depend on SMARCA2 for survival, supporting the complete functional inactivation of SMARCA4." (PMID 36633435, 2023). "Our results demonstrate that significant upregulation of ATAD2 and SMARCA4, and downregulation of SMARCA2 is consistently associated with enriched cancer stem cell‐like phenotype, respectively." (PMID 35049055, 2022). "The mammalian SWItch/Sucrose Non-Fermentable (SWI/SNF) helicase SMARCA4 is frequently mutated in cancer and inactivation results in a cellular dependence on its paralog, SMARCA2, thus making SMARCA2 an attractive synthetic lethal target." (PMID 36357397, 2022). "This permits pharmacological evaluation of the synthetic lethality concept of selectively targeting SMARCA2 in SMARCA4-deficient cancers in vivo and in vitro." (PMID 36216795, 2022). "In SMARCA4-deficient cancer, selectively targeting SMARCA2 would be a potential synthetic lethal therapeutic method to treat cancer." (PMID 35978859, 2022). "We have recently reported that the significant upregulation of the BrD family members ATAD2 and SMARCA4 and downregulation of SMARCA2 are associated with enriched cancer stemness." (PMID 36614001, 2022). "Dual allosteric inhibitors of the SMARCA2/SMARCA4 ATPases simulate synthetic lethality by curbing proliferation of SMARCA4-deficient cancers." (PMID 35323214, 2022). "To corroborate our results, we sought to perform the reverse experiments by restoring SMARCA4 or SMARCA2 in SMARCA4/2-deficient cancer cells." (PMID 34518526, 2021). "It is, however, frequently epigenetically silenced, which has been demonstrated, for example, by restoring SMARCA2 function in SMARCA2-deficient cancers using histone deacetylase (HDAC) inhibitors." (PMID 33941852, 2021). "PBRM1- and SMARCA2-expression were lost in the carcinoma but retained in the associated high-grade biliary intraepithelial neoplasia." (PMID 34118935, 2021). "Here we explore SMARCA4 alterations in 131,668 cancer patients and functionally profile their remodeling activity and ability to compensate for SMARCA2 loss." (PMID 33144586, 2020). "SMARCA4 and SMARCA2 function as mutually exclusive catalytic subunits of the SWI/SNF complex, and Hoffman et al112 demonstrated that depletion of SMARCA2 in SMARCA4‐deficient cancer cells led to cell cycle arrest and senescence." (PMID 32162380, 2020). "Alterations of BRM were reported in various cancer types, but only in some of them, SMARCA2 mutations were found." (PMID 31722744, 2019). "Insertions in the promoter sequence of SMARCA2 gene (at positions −741 and −1321) was specified as silencing-type polymorphism, leading to development of many types of cancer." (PMID 31722744, 2019).
cancer (continued). "Mutations in SMARCA2, a BRM-encoding gene as well as overexpression or epigenetic silencing were found in various human diseases including cancer." (PMID 31722744, 2019). "Re-expression of SMARCA4 or SMARCA2 into cancer cell lines deficient for these proteins decreases cell proliferation." (PMID 29391527, 2018). "Alternatively, other mutations in ACC are less prevalent in other cancers (e.g., SMARCA2), which if confirmed by additional studies warrant further investigation as drug targets in ACC." (PMID 26359351, 2015). "The researchers depleted SMARCA2 in SMARCA4-deficient cancer cell lines and xenograft models and observed cycle arrest, induction of senescence, and increased level of the repressive marker H3K9me3." (PMID 25391308, 2014). "Therefore, the selective depletion of SMARCA2 is particularly toxic for the respective cancer cells, while non‐malignant normal cells can compensate for SMARCA2 loss via SMARCA4 function." (PMID 40181550, 2026). "Because SMARCA4/SMARCA2-deficient and SS18–SSX fusion cancer cells depend on transcriptional upregulation of KREMEN2 due to SMARCA4/SMARCA2 deficiency and SS18–SSX fusion, we clarified that synthetic lethality is induced by repressing expression of KREMEN2 by simultaneous inhibition of CBP/p300." (PMID 39625239, 2025). "In this study, we show that simultaneous inhibition of a paralog pair (CBP and p300) causes synthetic lethality in SMARCA4/SMARCA2-deficient cancer cells and SS18–SSX fusion cancer cells; these results are similar to those obtained for SMARCB1-deficient cancer cells." (PMID 39625239, 2025). "PRT3789 is another potent and selective SMARCA2-targeted degrader that demonstrated synthetic lethality in SMARCA4-deficient cancers in vitro and in vivo and is currently in Phase I clinical trials for patients with SMARCA4 mutant solid tumors that express SMARCA2." (PMID 38390898, 2024). "Therefore, PROTACs that selectively target the non-functional BRD of SMARCA2/4 presents a potential avenue for exploiting the susceptibilities of cancer cells that rely on SMARCA2 or SMARCA4 for their survival." (PMID 38389844, 2024). "For example, SMARCA4 (BRG1) and SMARCA2 (BRM) are commonly mutated subunits in cancers." (PMID 35509102, 2022). "In contrast, the SMARCA4 paralogue SMARCA2 is less frequently mutated in cancer." (PMID 33941852, 2021). "Similarly, experimental suppression of SMARCA2 has been shown to be selective lethal to SMARCA4-deficient/SMARCA2 proficient cancer cells." (PMID 34518526, 2021). "Consequently, stimulation of ITPR3 expression through SMARCA2 reactivation by HDACi enhanced chemotherapy response in SMARCA4/2-deficient cancer cells." (PMID 34518526, 2021). "Due to its long-standing connection to cancer development, and the fact that the BRM/BRG complexes control the expression of many cancer-associated genes, there have been several recent studies that report the use of small-molecule inhibitors to target SMARCA2/4 bromodomains." (PMID 34298819, 2021). "BRG1-deficient cancer was found to be highly sensitive to BRM/SMARCA2 inhibition." (PMID 32019910, 2020). "Finally, one limitation of this study is our ability to address the potential for concurrent loss of SMARCA2 in SMARCA4-mutant cancers." (PMID 33144586, 2020). "The exact role of SMARCA2 missense mutations or duplication during development is still unclear; however, the SMARCA2 polymorphisms may lead to higher cancer risk, suggesting the role of human BRM as a cancer susceptibility gene, similarly to mice." (PMID 31722744, 2019). "In human cancer also concomitant loss of SMARCA2 and SMARCA4 expression has been described." (PMID 31406271, 2019). "SMARCA4 and SMARCA2 are mutually exclusive catalytic subunits of the SWI/SNF complex, and the inhibition of SMARCA2 activity appears to be synthetic lethal in cancer cells carrying SMARCA4-inactivating mutations, an effect that could be explained by paralogue insufficiency." (PMID 34262032, 2021).
cancer (continued). "A sgRNA-resistant SMARCA4 expression construct in which the SMARCA4 bromodomain is replaced with the bromodomain of BRD9 (SMARCA4res-BDBRD9) was designed to determine whether acute degradation of SMARCA4 represents a therapeutic approach against SMARCA2-deficient cancers." (PMID 31406271, 2019). "Likewise, SMARCA2 dependency was observed in SMARCA4-deficient cancer cells." (PMID 31769422, 2019). "For example, SMARCA4 mutant cancers become highly addicted to SMARCA2 function since the enzyme compensates for functional SMARCA4 loss in the ATPase module across all BAF complexes." (PMID 40181550, 2026). "Similar to SMARCA2, bromodomain inhibition only showed modest functional activity in preclinical cancer models." (PMID 40181550, 2026). "SMARCA4‐deficient cancer cells are highly dependent on SMARCA2 for survival, and targeting SMARCA2 in SMARCA4‐deficient cancers is expected to produce strong synthetic lethal effects." (PMID 41049269, 2025). "On the other hand, the sensitivity of ARID1A-deficient cancer cell lines to CBP/p300 dual inhibitors was intermediate between SWI/SNF WTs and the sensitive genotypes (SMARCA4/SMARCA2-deficient and SS18–SSX fusion)." (PMID 39625239, 2025). "We show that treatment with CBP/p300 dual inhibitors causes synthetic lethality in cBAF-deficient cancers such as SMARCA4/SMARCA2-deficient and SS18–SSX fusion cancers." (PMID 39625239, 2025). "In contrast, targeted protein degradation of SMARCA2/4, using the bromodomain-binding small molecule inhibitor to target PROTAC-driven degradation of the whole protein, robustly inhibits proliferation in numerous SMARCA2/4-dependent cancer cell lines." (PMID 41416925, 2025). "In a Phase I (NCT05639751) study investigating the novel SMARCA2 degrader PRT3789, patients with advanced cancers harboring SMARCA4 deficiency were treated to evaluate safety and efficacy." (PMID 41049269, 2025). "By exploring the predictability function in DepMap, we observed that low levels of SMARCA2 are positively correlated with SMARCA4 CRISPR knockout effects across all cancer cell lines." (PMID 39174852, 2024). "The study successfully demonstrated the targeted degradation of SMARCA2 over SMARCA4 and observed the therapeutic effectiveness in cancer models with SMARCA4 deficiency." (PMID 38389844, 2024). "We found that the homolog SMARCA2 decreased expression in cancer patients by 36% (p = 3.87e-10, adj p = 2.05e-09)." (PMID 38446332, 2024). "To elucidate the role of SWI/SNF ATPases in NB, we first evaluated SMARCA2/4 expression in the context of normal tissues and cancers." (PMID 39174852, 2024). "Family VIII inhibitors that are selective for PBRM1 bromodomains over those of SMARCA4 and SMARCA2 have also been developed and studied for anti-cancer effects." (PMID 38390898, 2024). "The potential use of allosteric inhibitors of SMARCA4/SMARCA2 is a significant breakthrough for a cancer type that has few treatment options." (PMID 38390898, 2024). "These included ARID1B, the paralog of which, ARID1A, is among one of the most frequently mutated genes in cancer, SMARCA4, and SMARCA2." (PMID 37500730, 2023). "The mutations of SMARCA2 in NCBRS disrupt the ATP-binding pocket, the Brace interface, and the DNA-binding interface, as occurring in cancer." (PMID 36633435, 2023). "SMARCA4 (BRG1) and SMARCA2 (BRM) are the two paralogous ATPases of the SWI/SNF chromatin remodeling complexes frequently inactivated in cancers." (PMID 37210563, 2023). "Two new studies exploring PROTAC-mediated degradation of SMARCA2 for cancer therapy solve an apparently intractable selectivity challenge with SMARCA4 by utilising the requirement for a productive ternary complex between the protein, PROTAC and ligase complex." (PMID 36720862, 2023). "The available data concerning SMARCA2 in cancer suggest that SMARCA2 function differs depending on the cancer type." (PMID 36674511, 2023).